HPSE (heparanase)
Diseases named in the same sentence as HPSE in open-access papers (continued):
Sharing a sentence is not in itself a finding about the gene and the disease.
breast carcinoma (continued). "Interestingly, also in breast cancer, fewer CTCs have been reported for brain metastatic patients when analyzed by the CellSearch system, and those CTCs that were competent to colonize the brain as a distant target organ site were predominantly EpCAM-negative but EGFR, NOTCH1 and HPSE-positive." (PMID 30572662, 2018). "Indeed, evaluation of heparanase expression in breast cancer cells reveals that more aggressive lines, such as MDA-MB-231 and MDA-MB-435, present high levels of heparanase, whereas MCF-7, a nonmetastatic and poorly invasive luminal breast cancer cell, presents low levels of the enzyme." (PMID 23984412, 2013).
myeloma (77 papers, 2008 to 2025). "Examination of available gene expression databases reveals that myeloma patients with high heparanase expression exhibited enhanced expression of acetyltransferase complexes and signaling pathways associated with myeloma growth and progression." (PMID 36980232, 2023). "Soluble heparanase is detected in the bone marrow of patients with myeloma associated with a high microvessel density." (PMID 36980254, 2023). "ChIP-on-chip data revealed that heparanase bound to regulatory regions of myeloma-related genes (i.e., CXCL12), encodes for SDF-1, CXCR4, CXCL2, CXCR3, CCL27, CX3CL1, and LCN2." (PMID 36980254, 2023). "Anti-myeloma chemotherapy has been linked with upregulation of HPSE expression, leading to enhanced tumor growth and chemoresistance." (PMID 33809973, 2021). "Examination of available gene expression databases revealed that myeloma patients with high heparanase expression exhibited enhanced expression of acetyltransferase complexes and signaling pathways associated with myeloma growth and progression." (PMID 32899927, 2020). "High heparanase in myeloma patients was associated with elevated patient PTEN levels compared to patients with low heparanase, consistent with PTEN stabilization and loss of tumor suppressor activity." (PMID 32899927, 2020). "Using myeloma cell lines, we discovered that heparanase binds to nuclear chromatin and is associated with an open chromatin organization consistent with previous findings that heparanase localizes to euchromatin." (PMID 32899927, 2020). "After 14 h treatment with bortezomib or melphalan, HPSE-high cells had significantly higher viability than the cells expressing mutated heparanase thereby demonstrating the importance of heparanase enzymatic activity in myeloma cell resistance to chemotherapy." (PMID 26624982, 2016). "Taken together, it is conceivable that the HPSE gene enhancer plays an important role in progression of the disease before diagnosis, and that the risk of multiple myeloma being diagnosed at later stages of the disease is higher in individuals with the AA genotype." (PMID 36980254, 2023). "For example, in multiple myeloma, high HPSE expression is linked to poor prognosis, and contributes to disease pathogenesis by inducing Sdc-1 shedding from the tumor cell membrane, which promotes sequestering of shed Sdc-1 bound growth factors in the tumor microenvironment." (PMID 32477959, 2020). "To determine whether there is an association between heparanase expression, chromatin remodeling and gene transcription activity in myeloma patients, we utilized the CoMMpass dataset Al13 available from the Multiple Myeloma Research Foundation (MMRF)." (PMID 32899927, 2020). "Additionally, latent heparanase is activated when it is cleaved by cathepsin L and studies of murine myeloma have shown that reduction in cathepsin L levels greatly reduces tumorigenesis and growth in mice, a potential link with loss of heparanase activation." (PMID 32899927, 2020). "Activation of genes that are associated with high heparanase expression in myeloma patients such as Notch, Sonic Hedgehog, Smad and the Tor complex C1 are among the major regulators of cancer stem cell activities, and their alterations are associated with tumorigenesis in myeloma." (PMID 32899927, 2020). "It was also reported that upregulation of heparanase in myeloma and breast cancer cells is associated with increased release of Syndecan-1, Vascular Endothelial Growth Factor (VEGF), and Hepatocyte Growth Factor (HGF) in EVs, leading to increased endothelial invasion through the ECM." (PMID 30925923, 2019). "Because heparanase was associated with the tumor cells that survive chemotherapy, we speculated that it was involved in myeloma resistance to therapy." (PMID 26624982, 2016).
myeloma (continued). "In addition to an association of heparanase with myeloma progression, Bret and colleagues discovered that Sulf2 expression in primary multiple myeloma cells were associated with a poor prognosis in two independent large cohorts of patients." (PMID 25105093, 2014). "Although the active form of heparanase has been identified as a key player in multiple myeloma and sarcoma, several other studies have linked the overexpression of the active form with aggressive primary tumor growth, invasion, and metastasis in certain cancer types." (PMID 25105093, 2014). "Interestingly, recent insights into the effects of heparanase-induced shedding of syndecan-1, an HSPG implicated in the pathobiology of multiple myeloma, revealed a unifying mechanism whereby heparanase expression promotes different aspects of disease progression." (PMID 30413079, 2018). "Of particular interest in the field is the role of heparanase in myeloma because its overexpression in the bone marrow environment was associated with a shorter event-free survival of patients with newly diagnosed myeloma treated with high-dose chemotherapy and stem cell transplantation." (PMID 25105093, 2014). "Studies in myeloma models revealed dual roles for HPSE in HGF activity: high serum levels of HPSE, shed SDC-1, and HGF correlate with poor prognosis, reflecting functional cooperation." (PMID 41301515, 2025). "When both syndecan‐1 and heparanase were highly expressed by myeloma cells, circulating levels of shed syndecan‐1 also increased, a phenomenon that positively correlated with poor prognosis and disease stage." (PMID 39600538, 2024). "Shed syndecan‐1 promotes the growth of myeloma in vivo, a process enhanced by heparanase through a dual action involving induction of syndecan‐1 synthesis and enzymatic removal of HS‐GAGs from the protein core." (PMID 39600538, 2024). "Previous studies have shown that heparanase expression by myeloma cells significantly increases local and systemic osteolysis." (PMID 36980254, 2023). "Heparanase leads to structural modifications of syndecan-1 resulting in syndecan-1 shedding from the myeloma cell surface." (PMID 36980254, 2023). "The role of HPSE in promoting the migration and invasion of endothelial cells, myeloma cells, and many other cancer cell types has been well documented." (PMID 37091070, 2023). "The upregulation of heparanase-1 expression has also been documented in hematological malignancies, e.g., for multiple myeloma, in which heparanase-1 represents a prominent biomarker for its early detection and a promising therapeutic target." (PMID 36680276, 2023). "High heparanase activity in myeloma cells correlates with myeloma growth, bone marrow angiogenesis, and osteolytic bone disease." (PMID 36980254, 2023). "Transfection of HPSE gene enhancer to myeloma cells resulted in increased expression of the HPSE gene and subsequent downregulation of the HPSE 2 gene." (PMID 36980254, 2023). "The effect of signal discrepancy between myeloma cells and normal cells of the tumor microenvironment is proposed as a mechanism for the involvement of heparanase in primary PS." (PMID 36980254, 2023). "Heparanase-neutralizing monoclonal antibodies block myeloma and lymphoma tumor growth and dissemination, attributable to a combined effect on the tumor cells and/or cells of the tumor microenvironment." (PMID 36980232, 2023). "This is of pathophysiological relevance in an oncological context, such as, e.g., in myeloma, chemotherapy can induce secretion of so-called chemoexosomes which deliver cargo, including the HS degrading enzyme heparanase to myeloma cells." (PMID 37370735, 2023). "Studies performed over the past two decades have shown that heparanase plays a major role in modulating the bone marrow microenvironment to support the progression of multiple myeloma." (PMID 36980254, 2023).
myeloma (continued). "In the present study, five previously identified and characterized functional HPSE gene SNPs were analyzed among patients with multiple myeloma." (PMID 36980254, 2023). "For instance, when myeloma cells were exposed to chemo-exosomes, the heparanase cargo was transferred, resulting in increased heparan sulfate degrading activity, ERK signaling activation, and increased shedding of syndecan-1 proteoglycan." (PMID 37612627, 2023). "Heparanase, the sole heparan sulfate (HS) degrading endoglycosidase, plays an important role in supporting and promoting myeloma progression, maintenance of cancer cell stemness, and resistance to chemotherapy." (PMID 36980254, 2023). "We suggest that an increase in heparanase-2 expression can lead to effective suppression of heparanase activity in multiple myeloma accompanied by extramedullary and osteolytic bone disease." (PMID 36980254, 2023). "We suggest that signal discrepancy between malignant myeloma cells and normal cells of the microenvironment provides a possible mechanism for the involvement of heparanase in primary EMD." (PMID 36980254, 2023). "Although aggressive myeloma cells exhibited the LR genotype, these cells have acquired a “fight” phenotype with high heparanase activity." (PMID 36980254, 2023). "Roneparstat, a potent inhibitor of HPSE enzyme activity, has been shown to have antimyeloma activity in mouse models and was successfully tested in a phase I trial in myeloma patients." (PMID 37091070, 2023). "We compared the efficacy of 2 to bortezomib, a proteasome inhibitor and standard treatment for multiple myeloma and lymphomas, and also explored the possibility of synergistic proteasomal and HPSE inhibitor treatment." (PMID 35881786, 2022). "For example, the treatment of bortezomib increased heparanase expression and heparanase-loaded exosomes in myeloma patients." (PMID 36358833, 2022). "Some studies have reported that upregulated HPSE correlates with poor prognosis in myeloma, colon, breast, and prostate carcinoma." (PMID 35840985, 2022). "As part of a complex network of remodelling enzymes, heparanase is known to promote myeloma stemness and tumorigenesis and synergize with chemotherapy to drive macrophage activation and cancer growth." (PMID 34982945, 2022). "A recent study also determines heparanase as a potential target for SARS-CoV-2 for a heparanase inhibitor Roneparstat (in phase I clinical trial for multiple myeloma therapy) reduces viral infection." (PMID 35958155, 2022). "It was also demonstrated that the tumor cells express a much higher level of heparanase upon relapse among patients with multiple myeloma following high-dose chemotherapy than was present prior to therapy." (PMID 34050190, 2021). "These authors suggest that anti-myeloma therapy stimulates the secretion of high heparanase content exosomes, facilitates ECM remodeling, changes tumor and stroma cell behavior, and contributes to chemoresistance." (PMID 33800172, 2021). "Heparanase has been shown to critically accelerate myeloma tumor growth and bone colonization, and the heparanase inhibitor Roneparstat has been examined in myeloma patients, yielding promising results." (PMID 34199150, 2021). "Another miRNA, miR-1252-5p, was also recently identified to regulate heparanase expression in multiple myeloma." (PMID 34681753, 2021). "Myeloma patients with advanced disease are known to express high levels of heparanase and to have high levels of shed Sdc1 in the tumor microenviroment and the blood." (PMID 34778093, 2021). "Enhanced levels of heparanase in myeloma cells led to a dramatic increase in phosphorylation of PTEN, an event known to stabilize PTEN, leading to its inactivity and loss of tumor suppressor function." (PMID 32899927, 2020).
myeloma (continued). "While PTEN emerged to be critical for stem cell maintenance playing a role in self-renewal, and proliferation, we recently published that heparanase promotes stemness properties of myeloma by increasing stem cell-related genes and proliferation." (PMID 32899927, 2020). "These heparanase-neutralizing mAbs profoundly attenuated myeloma and lymphoma tumor growth and dissemination of tumor xenografts produced by human lymphoma cells in preclinical models." (PMID 31963505, 2020). "A similar, although somewhat slower response in acH3 increase was seen in RPMI-8226 myeloma cells when exposed to heparanase." (PMID 32899927, 2020). "Patients suffering from multiple myeloma were found to have an increased level of heparanase in the bone marrow plasma, and over 90% of multiple myeloma patients had increased heparanase expression in gene array analysis." (PMID 32494847, 2020). "In the present study, we investigated the role of heparanase in chromatin remodeling in multiple myeloma." (PMID 32899927, 2020). "In part, heparanase and syndecan appear to regulate one another throughout the progression of myeloma and EMM." (PMID 33634031, 2020). "When treated with MNase, CAG myeloma cells in which heparanase had been knocked down by shRNA revealed mostly large bands of chromatin compared to smaller bands generated by MNase treatment of CAG HPSE Hi cells." (PMID 32899927, 2020). "We first examined the localization of heparanase in the cytoplasm and nucleus of wild-type (HPSE Lo) or heparanase-transfected cells (HPSE Hi) of the CAG human myeloma cell line." (PMID 32899927, 2020). "In myeloma, we have demonstrated that heparanase promotes osteolysis, angiogenesis and chemoresistance." (PMID 32899927, 2020). "We previously demonstrated that heparanase degradation of nuclear heparan sulfate enhances histone acetyltransferase activity in myeloma cells." (PMID 32899927, 2020). "It has been recently discovered that chemotherapy upregulates heparanase expression in myeloma surviving cells and induces secretion of chemoexosomes with heparanase loaded on surface." (PMID 31963505, 2020). "Myeloma cells also produce heparanase, an enzyme that cleaves heparanase sulfate chains of adhesive proteoglycans such as syndecan-1." (PMID 33634031, 2020). "Although heparanase has been studied extensively for its role in regulating tumor invasion and metastasis in myeloma and other cancers, little is known regarding the role of heparanase within the nucleus." (PMID 32899927, 2020). "Together, these findings reveal new roles of heparanase in the regulation of gene transcription in myeloma." (PMID 32899927, 2020). "Heparanase plays a major role in promoting myeloma progression, resistance to chemotherapy and maintenance of cancer cell stemness." (PMID 32899927, 2020). "For example, in multiple myeloma, heparanase trimming of the Sdc1 HS chains allows MMP−9-mediated shedding of Sdc1." (PMID 33243988, 2020). "Recent studies indicate that the interplay between the cell surface proteoglycan Syndecan-1 (Sdc-1) and HPSE have important functional connections in the progression of colorectal cancer and myeloma." (PMID 32477959, 2020). "Using myeloma cell lines, we report here that heparanase enhances chromatin accessibility and confirm a previous report that it also upregulates the acetylation of histones." (PMID 32899927, 2020). "Like heparanase, T5 significantly enhanced tumor development in a myeloma xenograft model, despite its inability to degrade HS." (PMID 31850210, 2019). "Most interestingly, the exposure of myeloma cells to various chemotherapy drugs dramatically enhanced the secretion of exosomes containing high levels of the 65 kDa form of heparanase as a cargo." (PMID 31850210, 2019).
myeloma (continued). "An additional form of cooperation between heparanase and syndecan-1 in the regulation of exosome biogenesis was first reported by the group of Sanderson in a study performed using multiple myeloma cell models with high and low heparanase expression." (PMID 30413079, 2018). "In multiple myeloma models, heparanase was found to represent a critical factor regulating levels of HS and syndecan-1 in the nucleus." (PMID 30413079, 2018). "Clinical anti-myeloma drugs were shown to induce syndecan-1 shedding in multiple myeloma cell cultures and in tumor xenografted mice, as well as the upregulation of heparanase expression and its release into conditioned medium." (PMID 30413079, 2018). "Targeting heparanase activity using Roneparstat, a modified heparin that is 100% N-acetylated and 25% glycol split, clearly diminishes aggressive myeloma growth in vivo." (PMID 26624982, 2016). "This is supported by our finding that cells with high heparanase are more resistant in vitro to anti-myeloma drugs than are cells with low heparanase expression." (PMID 26624982, 2016). "Our finding that heparanase drives ERK signaling to promote drug resistance is consistent with the known role of ERK in regulating myeloma cell proliferation, survival, drug resistance, and angiogenesis." (PMID 26624982, 2016). "The present work demonstrates that tumor cells that resist and survive therapy in myeloma patients have elevated levels of heparanase." (PMID 26624982, 2016). "This suggests that blocking heparanase activity in the presence of anti-myeloma drugs dramatically decreases chemoresistance to diminish myeloma tumor survival." (PMID 26624982, 2016). "The discovery that heparanase expression is high in the cells that survive chemotherapy in myeloma patients also supports the notion that heparanase plays an important role in drug resistance in vivo." (PMID 26624982, 2016). "Together these studies reveal the importance of heparanase in promoting chemoresistance and provide rationale for the clinical use of the heparanase inhibitor Roneparstat in combination with other anti-myeloma drugs." (PMID 26624982, 2016). "In cell-based models and in animal models of disseminated myeloma, use of the heparanase inhibitor Roneparstat both in combination with or after chemotherapy clearly diminished tumor burden and improved the overall outcome of therapy." (PMID 26624982, 2016). "By demonstrating that heparanase is elevated in tumor cells that survive even the most intensive therapy in myeloma patients, our present study has unveiled the importance of heparanase in the outcome of anti-myeloma therapy." (PMID 26624982, 2016). "Elevated heparanase expression by myeloma cells enhances their resistance to both bortezomib and melphalan and this resistance is reversedin vivo when mice are treated with the heparanase inhibitor Roneparstat25." (PMID 27408707, 2016). "Gene expression profiling of tumor cells from myeloma patients revealed that heparanase expression was high in the cells that survived and grew following chemotherapy." (PMID 26624982, 2016). "In fact, we have found that anti-myeloma drugs do promote heparanase expression and secretion in myeloma cell lines (unpublished observation)." (PMID 26624982, 2016). "The HPSE-high cells have been characterized extensively in these previous studies and they represent a physiologically relevant model for studying heparanase function in myeloma." (PMID 26624982, 2016). "To test this we treated cells having different levels of heparanase expression with different anti-myeloma drugs, bortezomib (BTZ), carfilzomib (CFZ) or melphalan (Mel) for 14 h and assessed their viability by MTT assay and ATPliteTM viability assay." (PMID 26624982, 2016). "HPSE-high and HPSE-low CAG human myeloma cells exhibit a 4-fold difference in their levels of heparanase and have levels comparable to those found in the bone marrow of many myeloma patients." (PMID 26624982, 2016).